IL6 (interleukin 6)
Diseases named in the same sentence as IL6 in open-access papers (continued):
Sharing a sentence is not in itself a finding about the gene and the disease.
tumor (continued). "IL‐17A and TNF synergistically induced the Th17‐promoting cytokines IL‐6 and IL‐1β as well as the Th17‐attracting chemokine CCL20 in mesothelial cells, indicating a reciprocal crosstalk that potentiates the tumor‐promoting role of Th17 cells in OC." (PMID 38566518, 2024). "IL6 upregulates MMP2 and MMP9 in OC, which degrades the extracellular matrix and makes passages for tumor invasion and cancer cell metastasis." (PMID 39766086, 2024). "Tumor cells have high expression of VEGF, IL-10, and IL-6; these tumor cells also highly express STAT3." (PMID 38571491, 2024). "The release of proinflammatory cytokines, such as IL-1, IL-6, IL-8, and TNF-α, by immune, stromal, and tumor cells activates tumor proliferative and pro-survival signaling pathways, such as NF-κB and STAT3." (PMID 38473997, 2024). "Conversely, cMSCs promoted tumor cell growth (including breast cancer, hepatocellular carcinoma and glioblastoma) through NO-mediated immunosuppression and MCP-1- and IL-6 -mediated macrophage trafficking and polarization towards an M2-like phenotype." (PMID 38779660, 2024). "This process acts as a vicious cycle, in which M2-type TAM cells are stimulated by the tumor itself, releasing factors like TNF and interleukins such as IL-6, IL-1b, and IL-10, which promote tumor proliferation and survival." (PMID 38248305, 2024). "Subsequently, M1 macrophages eliminate tumor cells by releasing NO, IL-12, IL-23, TNF-α, IL-6 and ROS." (PMID 38792234, 2024). "The abundant release of immune factors (Interleukin 6 and 8—IL6, IL8) by RCC cells dampens the immune response against the tumor and recruits different populations of immune cells." (PMID 38653823, 2024). "Leveraging sustained melanin production, BMB181 exhibits a robust capacity to induce tumor cell death through photonic hyperthermia as well as inhibit inflammatory cytokines such as tumor necrosis factor‐α (TNF‐α) and interleukin 6 (IL‐6) release." (PMID 38943265, 2024). "The expression of secreted protein‐coding genes, including MDK, HGF, RARRES2, GDF15, IL6 and MIA, was concentrated in the tumour cell‐enriched region, thus confirming the expression specificity of these signalling molecules." (PMID 38318640, 2024). "Marimastat treatment significantly reduced proinflammatory cytokines (Il‐1β and Il‐6), ER stress markers (CHOP and Grp78), and tumor markers (CD31 and AFP)." (PMID 38558505, 2024). "ETS1 is a transcription factor and ETS1 gene expression correlates with AXL, IL6, and EFEMP1 in TNBC cell lines and tumor tissues." (PMID 38762181, 2024). "MSCs are able to differentiate into a variety of cell types and promote tumor cell growth and metastasis through the secretion of cytokines and chemo-signals such as TGF-β and IL-6." (PMID 39697553, 2024). "Importantly, high baseline IL6 levels are associated with poorer outcomes, suggesting that Cediranib’s anti-angiogenic properties may help modulate IL6-related pathways, potentially enhancing therapeutic responses and addressing inflammation-driven tumor progression." (PMID 39766086, 2024). "Most tumor cells can produce IL-6, which promotes increased PD-L1 expression in neutrophils by activating JAK/STAT3 signal transduction, assisting the tumor in escaping immune surveillance." (PMID 39638788, 2024). "Our research provides new insight into the IL-6/STAT3 signaling regulation in distinct macrophage populations and further proves the therapeutic potential of gp130 blockage for tumor treatment." (PMID 38274367, 2024). "After the miRNA is upregulated, it can induce the production of IL-6 to form a STAT3/miRNA/IL-6 loop, or can regulate the expression of downstream target genes, thereby promoting tumor cell growth and accelerating cancer progression." (PMID 38172648, 2024). "CAFs secrete high levels of IL-6, which activates the JAK/STAT3 signaling pathway in CSCs, promoting their self-renewal and tumor-initiating capacity." (PMID 39519109, 2024).
tumor (continued). "Bazedoxifene, a third-generation SERM with IL-6/GP130 inhibitory effects, markedly potentiated the anti-tumor 5-FU activity in vitro and in vivo, implying a potential role for IL-6 pathway inhibition in reversing chemoresistance." (PMID 38689325, 2024). "IL-6 has been found to activate the JAK2-STAT3 signaling pathway by binding to the IL-6a chain and GP130 receptors, promoting tumor progression." (PMID 38519574, 2024). "A significant association between omega-3 fatty acids and muscle inflammation is established through the down-regulation of pro-inflammatory cytokines such as tumor TNF-α) and IL-6, as well as the reduction in ROS production." (PMID 39770885, 2024). "Macrophage-induced mesenchymal-like tumor cells then secrete increased amounts of CCL2, which recruits macrophages, and IL-6, which leads to M2 polarization, further propagating EMT in a positive feedback loop." (PMID 39555068, 2024). "MiR-24-1-5p expression was negatively correlated with tumor-related immune suppression pathways such as the IL2/STAT5 and IL6/JAK/STAT3 signaling pathways." (PMID 38840234, 2024). "Upon engagement with tumor cells, CAR T-cells undergo activation, releasing an array of inflammatory cytokines, including IFN-γ, IL-6, IL-10, TNF-α, and granulocyte macrophage-colony stimulating factor (GM-CSF)." (PMID 39521987, 2024). "Hence, the increase in CRP levels following IL-6 upregulation may not only represent a reaction to tumor progression but also signify tissue inflammation and damage, which could potentially function as a mechanism linking low mGNRI levels and unfavorable survival outcomes." (PMID 38839809, 2024). "For example, IL-6/JAK1 signaling pathway directed PD-L1 phosphorylation at Tyr112 site and promoted tumor immune evasion." (PMID 38638430, 2024). "High levels of pro-inflammatory cytokines such as IL-6 and TNF-α can promote tumor growth and metastasis." (PMID 39273009, 2024). "Tumor-derived factors such as IL-6, TNF-α, IFN-γ, AZGP1, and PTHrP, and tumor-host interactions influence metabolic programs in adipose tissue, including browning, lipolysis, inflammation, and thermogenesis." (PMID 38245780, 2024). "This enhances the infiltration of effector T cells (CD4+ and CD8+ T cells) into the tumor, promoting the release of pro-inflammatory cytokines (TNF-α, IL-6, and IL-12), killing the cancer and reversing tumor resistance." (PMID 39004737, 2024). "In ccRCC, in vitro experiments have shown that TIM-1 can induce IL-6 expression, thereby activating STAT-3, promoting angiogenesis through the IL-6/STAT-3 pathway, which is conducive to tumour growth and metastasis." (PMID 38831760, 2024). "The IL-6/JAK2/STAT3 pathway is involved in various biological processes, including tumor cell proliferation, apoptosis, migration, invasion, and cell cycle progression." (PMID 39845783, 2024). "We suggested that future use of this novel in vitro model might help identify the cellular source of IL-6 and IL-17 in mixed cultures of stromal + DLN cells, as well as the mechanisms implicated in the augmented production of those cytokines in the presence of tumor cells." (PMID 38540350, 2024). "Overall, the mTORC1/ERO1α/IL-6/STAT3/SLC7A11 signaling cascade, which is also present in human cancer cells, plays a critical role in ferroptosis resistance and tumor progression." (PMID 38610018, 2024). "IL-6 has been shown to activate the JAK/STAT3 signaling pathway, leading to enhanced tumor cell survival and proliferation." (PMID 39200315, 2024). "At the tumor microenvironment level, treatments with AgNPs-G and doxorubicin significantly increased (p ≤ 0.05) the levels of TNF-α, IFN-γ, and IL-6 compared to the control group." (PMID 39126001, 2024). "IL-6 produced by MDSCs can hinder the development and activity of CD4( +) T cells, ultimately promoting tumor development." (PMID 38717677, 2024).
tumor (continued). "CSCs have the ability to release interleukin-6 (IL-6), triggering the activation of STAT3 signaling in tumor cells and promoting tumor growth." (PMID 38926605, 2024). "Studies have shown that the downstream product of the cGAS-STING pathway, IL-6, can activate the STAT3 signaling pathway in tumors, thereby promoting tumor growth." (PMID 38523155, 2024). "Infiltration of immune cells, such as macrophages, into tumoral regions results in the release of proinflammatory cytokines (IL-6; IL-17; TNF-α), fostering tumor proliferation, survival, and invasion." (PMID 38892375, 2024). "While certain ILs like IL6 and IL8 show a role in CSC presence, the role of ILs related to circulating tumor cells (CTCs) is challenging to establish." (PMID 38791037, 2024). "In this way, by blocking the NFκB signaling, which is an important factor for tumor progression in inflammation-related cancers, and by decreasing TNF-α and some inflammatory cytokines such as IL-6, tumor progression can be alleviated." (PMID 39267853, 2024). "In order to investigate the effects of anlotinib on inflammatory factors within xenograft tumors, we examined the expression of IL-6, IL-8 and VEGFA in tumor tissues of four treatment groups by immunofluorescence staining." (PMID 39193386, 2024). "IL-6, in turn, in a positive feedback mechanism, boosts intra-tumoral EIF4A3 and CCL2 levels, further enhancing tumor cSERPINE2 biosynthesis and promoting TAM recruitment." (PMID 39068459, 2024). "IL-6 secreted by senescent tumor cells acted on TAMs, up-regulated TAMs CD73 expression through JAK/STAT3 signaling pathway, and suppressed anti-tumor immunity." (PMID 38323313, 2024). "IL-6 expression in OSCC has been related to high lymph node metastasis rates and poor tumor differentiation." (PMID 38644421, 2024). "This led to a fibroblast-driven increase in the production of IL-6 in the microenvironment surrounding KSCs, leading to EMT and accelerated tumor development in mice." (PMID 38519574, 2024). "In some in vitro studies (below), Fab rabbit anti-IL-6 or anti-IL-17 antibodies (Cedarlane Labs, ON, Canada) were used to explore cytokine roles in the TME in invasive tumor growth." (PMID 38540350, 2024). "For evaluating the role of PTEN expression on cGAS-STING activity and tumour immunogenicity, mRNA expression levels of interferon-stimulated genes, especially IFNB, IFIT2, IFI44, and IL6 were analysed." (PMID 38214828, 2024). "Studies have demonstrated that overexpression of FAM83A is associated with upregulation of pro-tumorigenic cytokines such as IL-6 and TGF-β, which are known to foster an immunosuppressive milieu conducive to tumor growth and progression." (PMID 38914812, 2024). "On the one hand, tumor cells with low or null SOCS1 expression, such as the A-549 and NCI-H1437 cell lines, would overexpress CD155 in response to IL-6." (PMID 39596207, 2024). "Gut microbiota promotes calcineurin and NFAT-dependent IL-6 release, and NFAT-dependent IL-6 promotes expression of B7-H3 by tumors and it inhibits CD8+ T cell-dependent anti-tumor immunity." (PMID 39497833, 2024). "Upon activation, CAFs can release a range of soluble factors that can enhance tumor invasion and metastasis, such as TGF-β, hepatocyte growth factor (HGF), epidermal growth factor (EGF), FGF and IL-6 cytokine." (PMID 39139454, 2024). "Specific bacterial strains induce the production of interleukin-6 (IL-6), interleukin-10 (IL-10), and transforming growth factor-beta (TGF-β), promoting tumor growth and evading immune surveillance by inhibiting cytotoxic T cells and natural killer (NK) cells." (PMID 39044834, 2024). "Mechanistically, CD248 + mechanoresponsive CAFs approached and lined the tumor nest to physically block the infiltration of CD8 + T cells and drug delivery, while IL6 + CCL2 + immunomodulatory CAFs induced therapeutic resistance with distinct IL-6 expression." (PMID 39334513, 2024).
tumor (continued). "The tumor exosomal circRNA cSERPINE2 is significantly elevated in BC and controls the MALT1-NF-κB-IL-6 axis in TAMs; it also increases IL-6 secretion that facilitates BC cell proliferation and invasion." (PMID 38731840, 2024). "We observed that interferon-alpha (IFN-α) and interferon-gamma (IFN-γ) very strongly induced the activation of the STAT1 protein, whereas IL-6 and IFN-α activated STAT3 and IL-4 activated STAT6 in all examined tumor cell lines." (PMID 38396958, 2024). "CAFs derived from ASCs secrete factors like IL-6, CXCL12, and Wnt proteins that maintain the stemness of cancer cells and promote tumor-initiating potential." (PMID 39519109, 2024). "TAMs are known to secrete a vast array of cytokines, chemokines, and growth factors, such as IL-6, IL-8, VEGF, and TGFβ-1, which all promote HCC cell proliferation, EMT, tumour cell migration, and metastasis." (PMID 39684877, 2024). "The IL-6/JAK/STAT3 signaling pathway drives tumor cell proliferation, invasion and metastasis and suppresses anti-tumor immune responses by reducing tumor antigen expression and decreasing responses to genotoxicity." (PMID 39007138, 2024). "Activated Th cells also release a variety of factors, such as IL-6, IL-11, IL-15, RANKL, and TNF-α, which promote osteoclastogenesis and bone resorption and provide a favorable environment for tumor bone metastasis." (PMID 38464516, 2024). "Aberrant activation of the IL-6/GP130 signaling pathway is commonly observed in various cancer types, contributing to tumor growth and resistance to therapy." (PMID 39451730, 2024). "In contrast, iCAFs are located further away from tumor cells and lack α-SMA and express high levels of the chemokines interleukin 6 (IL6) and C-X-C motif chemokine ligand 1 (CXCL1), which support tumor progression." (PMID 39273316, 2024). "In summary, IFI16 exerts its effects by modulating IL6, which activates the IL6/PI3K/AKT pathway, promoting the occurrence of ccRCC EMT, and ultimately enhancing tumor proliferation and metastasis." (PMID 38831470, 2024). "In CRC cells, tumor-derived lactate fuels H3K18 lactylation to prohibit RARγ gene transcription in macrophages, consequently enhancing IL-6 levels in the TME and endowing macrophages with tumor-promoting functions." (PMID 38812044, 2024). "Since the literature has demonstrated that IL-17, IL-6, and CSF3 promote lung tumorigenesis, we conjecture that MHV68 induces tumor promotion via induction of these cytokines." (PMID 39338937, 2024). "IL6 derived from CAFs creates a positive feedback loop, perpetuating CAF activation to support tumor cell proliferation and survival and stimulate other immune cells in the TME to facilitate invasion and metastasis." (PMID 39766086, 2024). "In the tumor immune microenvironment of RCC, IL-6 induces the expression of SOCS3 (suppressor of cytokine signaling-3), a negative regulator of cytokine signaling that promotes tumor cell invasion and metastasis." (PMID 38580797, 2024). "Our results suggest that biomarkers including IL-6, IL-8, MSI, TMB, and mRNA tumor gene signatures have predictive relevance across tumor types, particularly for cold tumors." (PMID 39190534, 2024). "Increased ROS production triggers the release of inflammatory factors such as IL-6 and TNF-α, altering the tumor microenvironment, which in turn affects the function of T cells and other immune cells." (PMID 38510247, 2024). "For example, increased ad libitum FASN contributes to the functional maturation of both Treg and TAM-M2 cells; conversely, inhibition of FASN impairs the tumor-promoting effects of TAMs by suppressing TNF-α, IL-6, IL-10, and ROS expression." (PMID 39227970, 2024). "And interleukin 6 (IL-6) is one of the best characterized and the highest expression pro-tumorigenic cytokines in TME, which can be secreted by both CAFs and tumor cells." (PMID 38213735, 2024).
tumor (continued). "The release of inflammatory factors, such as TNF-a, IL-6, and MCP1, by the visceral fat of obese individuals induces localized chronic inflammation, thereby establishing a microenvironment that fosters tumor progression." (PMID 38829434, 2024). "Markers of tumor burden and inflammation (LDH, CRP, IL-6, IL-10, TNF-α, ferritin, fibrinogen, D-dimer) were correlated with aph-PET and car-PET features." (PMID 38649972, 2024). "IL-6, CXCL2, and CXCL12 are cytokines/chemokines that are released by CAFs to regulate tumor immunity and angiogenesis." (PMID 39001545, 2024). "Since elevated levels of IL-6 in MHV68-infected wild-type mice were confirmed, the next question to address was how IL-6 would respond to infection in lung-tumor-bearing mice." (PMID 39338937, 2024). "This pattern is completely logical as inhibition of IL-10 allows for less immunosuppression, more angiogenesis, and more VEGF, IL-1β, TNF-α, IL-6, MMP-9, and NF-κB activation, which encourages tumor volume." (PMID 39451257, 2024). "Another study showed that tumor cells were able to induce stromal cells, including MSCs, to produce miR-214-rich EVs upon the activation of IL-6/STAT3 signaling, which favored the tumor dissemination." (PMID 39161894, 2024). "Key genes, including IL6, IL1B, and COL1A1, emerged from GSEA and tumor prediction analysis, highlighting the broad relevance of these genomic alterations across diseases." (PMID 39635438, 2024). "Exosomes released by tumor cells can activate the TLR/MyD88/NF-κB signaling pathway in macrophages, prompting the release of pro-inflammatory cytokines (such as IL-6, TNF-α, GCSF, and CCL2)." (PMID 38347830, 2024). "They demonstrated that the inhibition of CSF-1R and IL-6 in melanoma and non-small cell lung cancer (NSCLC) prevented tumor-induced DCs switching and enhanced the T cell-mediated immune response." (PMID 39457693, 2024). "Tumor-driven factors like TNF-α, GM-CSF, HMGB1, IL-6, CCL20, and hypoxia boost PD-L1 levels in neutrophils, dampening immune responses, particularly T cells." (PMID 38760815, 2024). "The summary of signaling pathway shows that ADAM17 activation is associated with many signaling pathways, such as inflammation response (e.g. IL-6, IL-1β, TNF, and TGF-β1), migration of tumor cells, tissue wound, and extracellular matrix organization." (PMID 38341954, 2024). "Subsequently, it was reported that serum IL-6 levels are also significantly increased in patients with CRC and positively correlated with tumour size." (PMID 38504172, 2024). "Therefore, IL-6 signaling may exogenously activate angiogenic and lymphangiogenic factors and endogenously promote the proliferation and survival of cancer cells, thereby supporting tumor growth." (PMID 38510850, 2024). "Further, we observed that targeting SIX4 attenuated the transformation of inflammation to cancer in intestinal epithelium via inactivating IL-6/STAT3/SIX4/c-JUN feedback loop, which subsequently suppressed DeltaNp63-mediated tumor stemness signals." (PMID 39309424, 2024). "Tumor size was positively correlated with levels of CXCL1 (r = 0.17, P = 0.048), CXCL8 (r = 0.18, P = 0.037), and IL6 (r = 0.27, P = 0.009)." (PMID 38965454, 2024). "In other cases, tumor cells driven by TNF-α and IL-6 directly affected wasting of skeletal muscle (a process that is also called cancer cachexia)." (PMID 38276543, 2024). "TAMs secrete cytokines such as TNF-α, TGF-β, and IL6, which regulate the CCA microenvironment and promote epithelial-mesenchymal transition, tumor growth, and metastasis." (PMID 39660136, 2024). "Macrophage‐derived IL‐6 activates the STAT3 and Hedgehog pathway in tumor cells, promoting proliferation and chemoresistance." (PMID 38426622, 2024). "IL-6 facilitates inflammatory reactions and the formation of the tumor microenvironment by activating the JAK/STAT3 signaling pathway, which aids in tumor growth and immune evasion." (PMID 38711918, 2024).